HDAC2 (histone deacetylase 2)
Diseases named in the same sentence as HDAC2 in open-access papers (continued):
Sharing a sentence is not in itself a finding about the gene and the disease.
medulloblastoma (11 papers, 2013 to 2025). A malignant, invasive embryonal neoplasm arising from the cerebellum. "More specifically, MYC-driven group 3 medulloblastoma cells have been shown to be highly susceptible to inhibition by HDACs and HDAC2 is highly expressed in group 3 medulloblastomas." (PMID 40862786, 2025). "Recent studies have suggested that HDAC5 and HDAC9 are significantly upregulated in high-risk medulloblastoma in comparison with low-risk medulloblastoma and be associated with poor survival 6.It also has been reported that HDAC2 expression is significantly associated with CRC progression." (PMID 35399729, 2022). "HDAC2 is a coactivator of c‐MYC in medulloblastoma by facilitating transcription factor licensing of c‐MYC." (PMID 39119816, 2025). "(2020) investigated the interaction between MYC and HDAC2 and reported that HDAC inhibition disrupts the MYC-HDAC2 complex in MYC-amplified medulloblastoma, leading to reduced chromatin binding of MYC." (PMID 40556679, 2025). "The inhibition of HDAC2 by mocetinostat induced the apoptosis of medulloblastoma cells by inhibiting Hh signaling." (PMID 36968022, 2023). "Pomeroy has reported a 3.133-fold increase in HDAC2 in desmoplastic medulloblastoma than in normal tissue samples (p = 5.47E-5)." (PMID 35359455, 2022). "After ruling out the unrelated medulloblastoma study, the contradictory expression profiles in the three studies on HDAC2 resulted in a perplexing conclusion, of which one indicated overexpression while the other two opposed." (PMID 34540896, 2021). "HDAC2 levels were also elevated in medulloblastoma when compared to CGP or preneoplastic regions of patched mice." (PMID 23951168, 2013). "HDAC2, a downstream effector of Hedgehog (Hh) signaling, was upregulated in medulloblastoma." (PMID 36968022, 2023). "Mocetinostat (MGCD0103), an HDAC1/HDAC2 inhibitor, is found to target Gli1 acetylation to truncate SHH signaling in medulloblastoma cells." (PMID 31788346, 2019). "LSD1, HDAC2, and HDAC3 are key targets for 4SC-202, and thus upregulation of these targets across the studied medulloblastomas makes 4SC-202 a more actionable therapeutic." (PMID 29099739, 2017). "Together, these results suggest not only a complex regulation of various HDAC family members during medulloblastoma development but also that possibly not only HDAC1 but other HDACs, such as HDAC2, 3, or 6 might contribute to tumor development." (PMID 23951168, 2013).
memory impairment (11 papers, 2013 to 2025). "It is very important to inhibit HDACs, especially HDAC2, to recover the memory impairment caused by aging or nervous system diseases, which may be due to remodeling chromatin and enhancing gene expression." (PMID 33542682, 2020). "Reversing the build‐ up of HDAC2 by short‐hairpin‐RNA ‐mediated knockdown activated these genes, reinstated structural and synaptic plasticity and abolished the neurodegeneration‐associated memory impairments." (PMID 29461008, 2018). "Earlier findings imply that over-expression of HDAC2 reduces dendritic spine density, resulting in reduced synapse formation, which triggers memory impairment." (PMID 41463361, 2025). "Actually, cinnamic acid as a treatment of TBI increases the expression of miR-455-3p, which in-turn suppressed the HDAC2 and reduce memory impairments." (PMID 34781166, 2021). "In summary, our findings consistently demonstrated that microglial activation increased HDAC2 expression leading to Bdnf and c-fos transcription repression in hippocampal glutamatergic neurons, which resulted in memory impairment." (PMID 31796106, 2019). "Given this evidence, it is reasonable to assume that acute stress-induced memory impairment may be mediated, at least in part, by HDAC2 activity, a relationship that remains unclear." (PMID 38635564, 2024). "To further support the role of HDAC2 in learning and long-term memory dysfunction, we showed that treatment with IN14 and PB, before the three behavioral tests explored here, reversed the memory impairment." (PMID 38635564, 2024). "Furthermore, HDAC2 knockdown also ameliorated the deficits in hippocampal CA1 long-term potentiation and memory impairment in contextual fear conditioning tests." (PMID 34899185, 2021). "That the free brain concentration of SAHA did not even briefly reach the IC50 of HDAC2 which is thought to be critical in fear memory and memory impairments in AD model mice is consistent with the lack of improvement of fear memory observed in the Tg2576 mice." (PMID 23922875, 2013).
cervical carcinoma (10 papers, 2011 to 2025). A carcinoma arising from either the exocervical squamous epithelium or the endocervical glandular epithelium. "In a study on human cervical cancer cell lines, HDAC2 was found to inhibit transcription of the genes of the Major Histocompatibility Complex, which are associated with the inflammatory phenotype in UM." (PMID 34439300, 2021). "Another HDAC that seems to be involved in cervical cancer is HDAC2, whose overexpression was reported by Huang's team." (PMID 33634093, 2020). "It has been proved that cinnamic acids, especially dihydroxycinnamic (caffeic) acid, have the ability to interact with HDAC2 (histone deacetylase 2), inhibiting its activity ex vivo and in vitro and inducing apoptosis of colon and cervical cancer cells." (PMID 33049979, 2020). "This HDAC isotype selectivity may be related to the drugs' activity against the gynecologic cancer cell lines as HDAC 1/2/3 have been implicated in ovarian tumor malignancy and growth, while HDAC2 is overexpressed in cervical cancer carcinogenesis." (PMID 30576957, 2019). "HDAC2 may mediate Parkin acetylation and activate mitophagy in cervical cancer." (PMID 39075515, 2024). "It has been reported that CBX7 hinders HDAC2 activity to promote CDH1 expression and block epithelial-mesenchymal transition in thyroid, pancreatic and cervical cancer cells 19, 22-24." (PMID 35342353, 2022). "For cervical cancer cells, a high expression of HDAC1, HDAC2, and HDAC6 was found." (PMID 33634093, 2020). "Interestingly, although a previous study has demonstrated that HDAC2 inhibition increased apoptosis in HeLa cervical cancer cells, our results indicated that HDAC2 inactivation did not induce apoptosis, while it strongly induced G1/S arrest in cell cycle transition." (PMID 22132221, 2011).
triple-negative breast carcinoma (10 papers, 2018 to 2026). An invasive breast carcinoma which is negative for expression of estrogen receptor (ER), progesterone receptor (PR), and human epidermal growth factor receptor 2 (HER2). "In summary, this present study demonstrated that increased HDAC-2 expression is associated with very important clinicopathological parameters of triple negative breast cancer patients, such as survival, recurrence and disease stage." (PMID 38201636, 2024). "Functional studies revealed that the binding of the YY1/p300/histone deacetylase 2 (HDAC2) complex to the GUSBP11 promoter is responsible for its reduced expression in triple-negative breast cancer cell lines." (PMID 41431719, 2026). "Meta-analyses of gene expression showed a significant reduction in HDAC1 and HDAC2 expression in triple-negative breast cancer samples." (PMID 40375313, 2025). "This current study aims to investigate the expression of HDAC-2 by immunohistochemistry in tissue samples from triple negative breast cancer patients and its relationship to the clinicopathological characteristics of the tumor and the prognosis of the patient." (PMID 38201636, 2024). "In this study, we aimed at assessing the clinical importance of HDAC-2 in triple negative breast cancer." (PMID 38201636, 2024). "Increased HDAC-2 expression was observed in 11 (27.5%) of the 40 cases of triple negative breast cancer that showed positive HDAC-2 staining." (PMID 38201636, 2024). "Our results indicated that triple negative breast cancer shows a higher percentage of HDAC-2 overexpression, in comparison with non-triple negative breast cancer tissues." (PMID 38201636, 2024). "The 40 triple negative breast cancer tissue specimens showed a higher percentage of HDAC-2 overexpression, compared to the 98 non-triple negative breast cancer tissues that met the study criteria (27.5% vs. 12.2%, p = 0.029)." (PMID 38201636, 2024). "So far, only three studies have explicitly investigated the role of HDAC-2 in triple negative breast cancer." (PMID 38201636, 2024). "In this present study, we investigated the clinical importance of the expression of HDAC-2 in triple negative breast cancer." (PMID 38201636, 2024). "This current study demonstrated that increased HDAC-2 expression correlates with significant clinicopathological parameters of triple negative breast cancer patients, such as survival, recurrence, and disease stage." (PMID 38201636, 2024). "These two compounds have IC50 values for HDAC1 and HDAC2 higher than 10 μM, and compound 6 showed in vitro efficacy in suppressing the cancer stem cell subpopulation of triple-negative breast cancer by downregulating β-catenin." (PMID 29498635, 2018). "Immunohistochemical HDAC-2 expression in triple negative breast cancer." (PMID 38201636, 2024). "HDAC-2 overexpression correlated with prolonged overall survival (OS) and disease-free survival (DFS) in triple negative breast cancer." (PMID 38201636, 2024).
lymphoma (9 papers, 2016 to 2025). A malignant (clonal) proliferation of B- lymphocytes or T- lymphocytes which involves the lymph nodes, bone marrow and/or extranodal sites. "In both in vitro and in vivo settings, genetic co‐depletion of Hdac1 and Hdac2 was pro‐apoptotic in Eμ‐Myc lymphoma, and this behavior was mimicked by the HDAC1/2‐specific agent RGFP233." (PMID 39428967, 2024). "HDAC2 not only facilitates lymphomagenesis, but is also required for lymphoma maintenance." (PMID 29721185, 2018). "Using a spectrum of human lymphoma specimens, we observed high levels of HDAC1 and HDAC2 protein expression in the vast majority of ALCL, angioimmunoblastic T cell lymphoma (AITL), and PTCL cases." (PMID 40175628, 2025). "Interestingly, we found that human HDAC1, but not human HDAC2, mRNA expression is increased in some Burkitt’s lymphoma (BL) and diffuse large B cell lymphoma (DLBCL) cancer cell lines and human lymphoma samples, when compared to other cancer cell lines or other human cancer samples, respectively." (PMID 27886239, 2016).
non-small cell lung carcinoma (9 papers, 2013 to 2024). A group of at least three distinct histological types of lung cancer, including non-small cell squamous cell carcinoma, adenocarcinoma, and large cell carcinoma. "HDAC2 is involved in the resistance of tumor cells, inhibition of HDAC2 expression increased the sensitivity of cisplatin in non-small cell lung cancer." (PMID 38087046, 2024). "We further explored possible molecular mechanism(s) by which inhibition of HDAC2 negatively regulates survivin expression and elucidated the relationship between inhibition of HDAC2 and radiosensitivity in non-small-cell lung cancer cells." (PMID 25605253, 2015). "Treatment with valproic acid (VPA) enhanced cisplatin sensitivity of non-small-cell lung cancer (NSCLC) cells via HDAC2 mediated down-regulation of ABCA1, further reinforcing the idea that overexpression of ABCA1 in lung cancer can be associated with resistance to therapies." (PMID 34281263, 2021). "Inhibition of HDAC1 and HDAC2 enhanced the radiosensitivity of non-small cell lung cancer." (PMID 24650256, 2014). "Exposure of the human non-small cell lung cancer lines A549 and H358 to the antiepileptic drug valproate led to downregulation of ABCA1 mRNA and ABCA1 protein levels through a histone deacetylase 2-(HDAC2)-mediated mechanism." (PMID 34977908, 2021).
pulmonary fibrosis (9 papers, 2017 to 2024). Chronic progressive interstitial lung disorder characterized by the replacement of the lung tissue by connective tissue, leading to progressive dyspnea, respiratory failure, or right heart failure. "Evidence suggests that HDAC2 is mainly involved in the chronic progression of pulmonary fibrosis, and inhibition of HDAC2 can alleviate bleomycin-induced pulmonary fibrosis in mice." (PMID 37951958, 2023). "The role of HDAC2 inhibition in the treatment of lung fibrosis is still to be determined." (PMID 35865549, 2022). "In particular, the pulmonary expression of nuclear HDAC4 significantly increased following MV-augmented lung fibrosis compared with HDAC2; this indicates that class II HDAC4 intensely translocated from the cytoplasm into the nucleus in the injured lungs, whereas class I HDAC2 was not altered." (PMID 28234968, 2017). "Oxidative stress and epigenetic alterations, including the overexpression of all class I and II histone deacetylases (HDACs), particularly HDAC2 and HDAC4, have been identified as key molecular mechanisms driving pulmonary fibrosis." (PMID 37893021, 2023). "Many studies have reported overexpression of all Class I and II HDACs, especially HDAC2 and HDAC4, in pulmonary fibrosis." (PMID 37893021, 2023). "It was reported that HDAC2 was crucial for the chronic progression of lung fibrosis, while HDAC4 was crucial for the initial response to lung fibrosis." (PMID 37893021, 2023). "Further, HDAC2 and HDAC3 have been observed to be upregulated in various rodent models of pulmonary fibrosis, with predominant localisation in fibrotic lesions and lung fibroblasts." (PMID 35626663, 2022).
adenoma (8 papers, 2013 to 2025). A neoplasm arising from the epithelium. "HDAC2 overexpression in CRC is responsible for adenoma–carcinoma progression, while HDAC2 mutations are associated with treatment resistance." (PMID 37046620, 2023). "Their findings also indicated an elevated level of HDAC2 in adenocarcinoma compared to adenoma, highlighting its role in the transition from adenoma to adenocarcinoma." (PMID 40239010, 2025). "Loss of either Brg1 or histone deacetylase 2 can lead to GC resistance in ACTH-secreting adenomas, since Brg1 stabilizes the interaction between GR and histone deacetylase 2 to suppress proopiomelanocortin gene transcription." (PMID 35054858, 2022). "When comparing cancer and non-cancer cases, HDAC2 expression was significantly associated with adenoma progression to carcinoma (P = 0.002), with a discriminative power of 0.74." (PMID 36119474, 2022). "HDAC2 nuclear expression levels were higher in 81.9%, 62.1%, and 53.1% of CRC, adenoma, and normal tissues, respectively (P = 0.002)." (PMID 36119474, 2022). "In human resection samples, we found that HDAC2 expression was also about 2-fold higher in patients harboring an adenoma elsewhere in the colon compared to the control (no dysplasia) group (p<0.05, n = 12 subjects)." (PMID 23724067, 2013). "We performed a PCR array for HDAC1, HDAC2, HDAC3, HDAC5 and HDAC7 on human rectal biopsies from patients with or without an adenoma in the colon (n = 86 subjects total)." (PMID 23724067, 2013).
Anxiety (8 papers, 2016 to 2024). Intense feelings of nervousness, tension, or panic often arise in response to interpersonal stresses. "In another study, P rats, bred for selective alcohol preference, have been shown to have higher Hdac2 expression levels and a concomitant decrease in H3K9ac accompanied by anxiety-like behaviors." (PMID 35998298, 2023). "Upon acute exposure to ethanol, P rats were found to have reduced expression levels of HDAC2, increased levels of H3K9ac at Bdnf exon IV promoter, and a diminished anxiety phenotype." (PMID 35998298, 2023). "Lactate, a metabolite produced by exercise, induced resilience to social defeat stress and reversed social avoidance behavior and anxiety by modulating the activity of HDAC2 and HDAC3." (PMID 34065586, 2021). "This anxiety was associated with increased global HDAC activity and increased HDAC2 and HDAC4 isoform expression in the CeA and MeA, leading to decreased levels of activating histone 3 lysine 9 (H3K9) acetylation." (PMID 27303256, 2016). "Infusion of an HDAC2 siRNA into the CeA reverses these molecular effects while normalizing the dendritic spine density, anxiety-like behaviors, and alcohol intake seen in these animals." (PMID 27303256, 2016). "Though the mechanism for HDAC2 inhibition by ethanol is unclear, the anxiolytic effect of alcohol in social situations can be inferred from this model, as it appears that alcohol consumption attenuates anxiety symptoms and phenotypes on an epigenetic level." (PMID 35998298, 2023). "Additionally, higher expression of Hdac2 in the AMY of alcohol‐preferring rats compared to nonalcohol‐preferring rats also implicated it in anxiety‐like and in alcohol‐drinking behaviors." (PMID 33216461, 2021).
atherosclerosis (8 papers, 2013 to 2025). A disease characterized by the build-up of fatty material and calcium deposition in the arterial wall resulting in partial or complete occlusion of the arterial lumen. "Experimental evidence suggests that the inhibition of HDAC2 may mitigate certain adverse effects associated with a high-calorie diet, including high-fat diet-induced hypertension and increased susceptibility to atherosclerosis." (PMID 40806702, 2025). "In atherosclerosis, overexpression of HDAC2 in endothelial cells under proatherogenic conditions and oxidative injury suppresses the expression of Arginase2 (ARG2), which further reduces the expression of endothelial nitric oxide synthase (eNOS)." (PMID 36909892, 2023). "Here we focused on five genes (Tgfbr1, Zeb1, Hdac2, Rab5a, and Ets1), which were all identified by miFDR alone, and discussed their potential roles in the context of diesel particle exposure and atherosclerosis." (PMID 24564975, 2013). "In another study, HDAC2 was shown to protect against atherosclerosis." (PMID 40710369, 2025). "In summary miR-410 and alkyl-glycerophosphate (AGP) play a role in atherosclerosis by downregulating HDAC1 and HDAC2, leading to increased inflammation and endothelial dysfunction." (PMID 40660005, 2025). "Cyclic phosphatidic acid (cPA) inhibits this downregulation of HDAC2 in endothelial cells via the AGP, thus attenuating the effects of atherosclerosis." (PMID 40660005, 2025). "HDAC2 can reduce the interaction between CIITA and RFX5 by protein degradation and deacetylation of CIITA, thereby counteracting the activity of CIITA and promoting the development of atherosclerosis." (PMID 40710369, 2025).
brain tumor (7 papers, 2020 to 2026). "Also, the inhibition of HDAC2 activity disrupted the interaction with SMAD3, resulting in the loss of stem cell-like characteristics of brain tumor cells." (PMID 39063083, 2024). "The role of histone deacetylase 2 (HDAC2) in GBM appears to regulate acetylation of histones 3 and 4 which were in turn found to potentiate brain tumor stem cell (BTSC) self-renewal." (PMID 41139700, 2026).